AFP (alpha fetoprotein)
Diseases named in the same sentence as AFP in open-access papers (continued):
Sharing a sentence is not in itself a finding about the gene and the disease.
tumor (continued). "However, the serum AFP level and HBV-DNA level were higher in patients with tumor response than those in nonresponders." (PMID 35342396, 2022). "Tumor markers (CEA, AFP, CA125, CA199 and CA153) do not accurately reflect the disease." (PMID 36249004, 2022). "More aggressive tumor lesions were shown in the DEN-treated WT mice by positive Ki67 and AFP staining, whereas DEN-treated knockout and DEN/TSAHC-treated WT mice showed fewer tumors with less positive or negative Ki67 and AFP staining." (PMID 34921636, 2021). "However, MDK and combinations of AFP + MDK, GPC3 + OPN have not been studied yet, therefore, it is a question of future research to investigate effectiveness of using these tumor markers in combination." (PMID 34513063, 2021). "Whereas the data showed no upregulation of tumor markers such as β-human chorionic gonadotropin (β-HCG), alpha-fetoprotein (AFP), and lactate dehydrogenase (LDH), scrotal ultrasonography and magnetic resonance imaging indicated the existence of paratesticular and inguinal lesions respectively." (PMID 33816267, 2021). "Tumor burden was not statistically different between groups prior to RIT, with mean serum AFP concentrations of 185,986 ± 127,154 ng/mL in the no treatment control group, 166,370 ± 119,541 ng/mL in the αGPC3-DOTA control group, and 180,613 ± 155,557 ng/mL in the 90Y-DOTA-αGPC3 group (p = 0.97)." (PMID 33580090, 2021). "Tumor markers including CEA, CA125, CA199, NSE and AFP were negative." (PMID 34629105, 2021). "Importantly, CD90+ cells do not express conventional tumor markers for HCC, such as PIVKA-II or AFP." (PMID 34445353, 2021). "The median serum levels of AFP, PIVKA-II, GPC-3, adiponectin and IL-6 were significantly higher in patients with HCC compared to those without tumor (all p < 0.001); only the plasma leptin values were not different between the two groups of patients (p = 0.649)." (PMID 34064999, 2021). "There are tumor biomarkers that may be increased, such as CA 15-3, SCC, CA 125, and AFP, and others that are not so much, such as the example of CEA, CA 19-9, LDH, AMH, and HE-4." (PMID 33425755, 2020). "In addition to negative portal or venous washout and negative arterial enhancement in images, age > 56.61 years, tumor size > 12.45 mm, HCV carrier status, and ln(AFP) > 1.954, are useful indicators for the early detection of small HCCs." (PMID 33193879, 2020). "On the basis of the results of log-minus-log plot ANOVA, Brown-Forsythe, and Bartlett’s tests, preoperative significant predictive factors including LSG, ICGR15, AFP, PIVKA2, tumor size, and HBV did not have interaction effect and confounders, and proportional hazard was confirmed." (PMID 33272298, 2020). "Moreover, circ-TTC17 in plasma was reported without any aberrant relationships to tumor size, differentiation, gender, age, or common clinical biomarkers (e.g., SCCA, CEA, and AFP) in ESCC cases." (PMID 33392180, 2020). "With respect to tumor factors, fibronectin levels were not significantly correlated with maximum tumor size, tumor number, BCLC stage, microvascular invasion, encapsulation, histologic grade, and AFP levels." (PMID 33277619, 2020). "The tumor cells of the adenocarcinoma component had periodic acid-Schiff (PAS)-positive globules and were positive for sal-like protein 4 (SALL 4) and negative for α-fetoprotein (AFP) or human epidermal growth factor receptor type 2 (HER2)." (PMID 31960152, 2020). "Together, these data suggest that AFP has a negative influence on cell apoptosis and that inhibiting the extrinsic apoptotic pathway may exert a principal effect on HCC cell growth and tumor progression." (PMID 33009373, 2020). "Tumor markers (CEA, AFP, CA19–9, CYFRA21-1, NSE and SCC) were all negative." (PMID 31046794, 2019). "However, the patient had no smoking history, no other site malignancy and no tumor markers (CEA, AFP, CA19–9, CYFRA21-1, NSE and SCC) positive." (PMID 31046794, 2019).
tumor (continued). "Sorafenib treatment of HepG2 tumours slightly increased the expression of ΑFP, while sorafenib treatment of stem‐like tumours reduced the expression of CD133 but did not induce a significant modification of AFP or ALDH1A1." (PMID 30959553, 2019). "However, an absence of AFP overproduction did not exclude a diagnosis of IHA and the capacity of tumor tissue to produce AFP had no impact on prognosis." (PMID 29416804, 2018). "Studies performed on IGF1R tissue expression, showed that tumor expression was significantly higher than in the surrounding tissue and correlated with the HCC differentiation and cirrhosis, but not to the number or size of tumors, HBV infection, and AFP level." (PMID 29702590, 2018). "However, other variates including AFP, TNM stage and tumor stage had no significant influence on the overall survival time." (PMID 30560088, 2018). "In addition, we also noticed that the serum AFP level, a most commonly used tumor biomarker for HCC, was higher in C57-HBV mice no matter bearing tumor burden or not than that in C57 mice at 8 months’ post injection." (PMID 28584302, 2017). "However, symptomatic diagnosis, LMR, tumor size, tumor location, albumin, age, CA199, CEA, AFP, CA125 and ECOG-PS were not significant predictors of DFS." (PMID 29235538, 2017). "As serum levels of AFP can be elevated in NMC, immunohistochemistry for NUT should be considered in all poorly differentiated carcinomas arising in midline structures without glandular differentiation, regardless of the levels of tumor markers." (PMID 27855672, 2016). "Finally, AFP is not part of the BCLC staging system but can serve as a surrogate for occult vascular invasion, distant metastases, or aggressive tumor biology." (PMID 27116028, 2016). "Tumor cells were positive for CK7 EMA, CKAE1/AE3, CD15, CA-125, while immunoreaction for Calretinin, WT1, estrogen, and progesterone receptors, cytokeratin 20, CD10, alpha fetoprotein, CDX2, TTF1, and thyroglobulin were all negative." (PMID 27912770, 2016). "However, in multivariate analysis, only tumor size and advanced TNM stage were independent predictors of DFS and OS; both DCP and AFP failed to be independent predictors of DFS and OS." (PMID 27070780, 2016). "In the cohort of 246 patients, positive expression of Axl in their tumors was closely related with the absence of tumor capsule, presence of MVI, multiple nodules and high serum AFP concentration, which all pointed to an aggressively invasive property of the tumor." (PMID 27182739, 2016). "Kim J and coworkers determined plasma levels of OPN (ELISA), as well as AFP and PIVKA II, in 62 patients with HCC (69 % HBV, 10 % HCV, 3 % alcohol related), in 60 patients with chronic liver disease without tumor (83 % HBV, HCV 3 %, 10 % alcohol related) and in 60 healthy controls." (PMID 26122937, 2015). "Moreover, regardless of tumor differentiation grade, tumor size, TNM stage, and aspartate transaminase (AST) and AFP levels, peritumoral CXCL17 was a good predictor of recurrence (all P<0.05)." (PMID 25303284, 2014). "Serum tumour markers beta HCG, AFP and LDH were not increased." (PMID 24321309, 2013). "Third, the patient was negative for AFP and CEA- and CA-type tumor markers." (PMID 23957966, 2013). "In the AFP-negative HCC the rate of tumor growth would probably be expected to be relatively slow and tumor staging might be lower than in AFP-positive HCC." (PMID 23981851, 2013). "However, there are other important predictors of recurrence and patient survival that have not been included in the current selection system such as AFP/AFPL3% levels, tumor differentiation, and microvascular invasion." (PMID 24455285, 2013). "In this case, increased AFP levels could stem from fibrosis, necrosis, and apoptosis triggered by the hepatitis B virus’s invasion of hepatocytes, despite a negative HBV DNA test, or they may result from tumor rupture." (PMID 41293148, 2025).
tumor (continued). "Although serum biomarkers like AFP, CD147, and IL-6 may be biologically correlated (e.g., inflammation and tumor progression pathways), the VIF test confirmed no severe multicollinearity (all VIF < 10), suggesting their independent contributions to the nomogram are statistically valid." (PMID 40919145, 2025). "Elevated levels of tumor markers, including AFP or PIVKA‐II, were reported in six patients before the diagnosis of small bowel metastasis and included three (21%) patients with no subjective symptoms, apart from elevated tumor markers, during regular follow‐up." (PMID 41318218, 2025). "The AFP level, liver function, and TNM stage in the CXCR2+ low group were significantly different from those in the CXCR2+ high group, while other clinicopathological features such as age, gender, tumor number, tumor diameter, and HBsAg were not significantly different." (PMID 37403022, 2023). "Computed tomography (CT) result showed a tumor occupying nearly the entire subsegment I with characteristics of HCC, at size 46 mm, compressing the inferior vena cava, close to the hepatic pedicle, right and left hepatic veins but not invasive, no thrombus portal vein, and serum AFP > 400 ng/ml." (PMID 35115011, 2022). "However, a previous study reported that an elevated level of preoperative AFP and/or PIVKA-II correlated with early postoperative recurrence (≤6 months) because early phase recurrence represents metastasis rather than a secondary de novo tumor." (PMID 35085305, 2022). "In this clinical study, targeting AFP+ HCC tumors with AFP-specific CAR-T cells resulted in one complete response out of four patients and one patient had a partial response with 100% reduction of targeted tumors and only one non-targeted tumor nodule remained at therapy week eight." (PMID 34209393, 2021). "γ-GT is reported to improve tumor development and progression, which could be regarded as an alternative biomarker of HCC diagnosis, especially for those with clinically negative AFP." (PMID 34663242, 2021). "Regarding preoperative tumour biomarkers, there were significant differences in carbohydrate antigen 125 (CA125) (P = 0.001) and carbohydrate antigen 199 (CA199) (P = 0.016) but not in carcinoembryonic antigen (CEA) (P = 0.769) or alpha fetoprotein (AFP) (P = 0.487)." (PMID 33485347, 2021). "In another study comparing patients with HCC managed by a multidisciplinary tumor board (MDTB) to those who were not, it was demonstrated that patients managed by MDTB were more likely to present with cancer at earlier stages and with lower serum alpha-fetoprotein (AFP)." (PMID 34638333, 2021). "Patients with small HCCs were older than patients with non-HCC liver nodules and had higher AFP levels, higher alanine transaminase (ALT) levels, higher aspartate aminotransferase (AST) levels, prolonged prothrombin time (PT), lower platelet counts, and larger tumor sizes." (PMID 33193879, 2020). "Serum miR-223-3p had a negative correlation with tumor size (r = -0.312, P = 0.008) and BCLC stage (r = -0.410, P<0.001) but did not correlated with other clinical parameters, including sex, age, biochemical parameters, AFP level, HBeAg status and HBV DNA level." (PMID 32330203, 2020). "Its expression level positively correlated with tumor size, Child–Pugh classification, or tumor stage of HCC, but not with age, sex, HBV infection time, etiology, alanine aminotransaminase, aspartate aminotransaminase, total bilirubin, prothrombin time, and AFP levels." (PMID 32923383, 2020). "However, our patient's tumor marker test (CA199, CEA, AFP, CA125, CA153) was negative." (PMID 31626091, 2019). "In addition to the antigens described here, the original tumor was positive for CKC, CK7 and CK 5/6, negative for GATA3, CDX2, ERα, CK20,p63, AFP, CA19.9, TTF1 and PAX 8 and with patchy/focal staining for calretinin, CD10, RCC, BerEP4 and WT‐1 (data not shown)." (PMID 30109783, 2018).
tumor (continued). "Although no clear trend for AFP or L3% was observed during the course of either treatment, the increment ratio of DCP during the course of treatment was significantly larger in the monotherapy group, suggesting a better tumor control capability from the combination therapy (p < 0.0001)." (PMID 28490356, 2017). "However, whether the expression of α-fetoprotein (AFP) was positive or negative in patients' serum, CSIG protein levels were higher in most HCC samples than in adjacent non-tumor tissues." (PMID 25749381, 2015). "This may be because, in contrast to AFP, DCP can be produced in surrounding non-cancer tissues after being stimulated by HCC, which might have attenuated the correlation between DCP response and radiologic tumor response by the mRECIST criteria." (PMID 23282286, 2013). "Early detection is possible with ultrasound scanning and AFP monitoring, although the use of AFP as a screening test is complicated by frequent false positive and false negative results, so early diagnosis of HCC would not be difficult if tumor markers and medical imaging were combined." (PMID 27785253, 2013). "In addition, cytoplasmic overexpression of ZEB2 in HCC tissues was found to correlate with low serum AFP level, small tumor size and well tumor differentiation, and negative correlation of overexpression of cytoplasmic ZEB2 in PLTs and serum AFP level was also observed." (PMID 22393452, 2012). "Moreover, unlike AFP, measuring SNHG1 levels appears to improve the prediction of prognosis for HCC patients, providing clinicians with better insights regarding the aggressiveness of the tumor, the survival likelihood, and the selection of appropriate therapies from the outset." (PMID 39200161, 2024). "In addition, CTC‐related variables were especially helpful in AFP‐negative patients; 70 out of 156 HCC patients in the cohort (44.87%), 16 of whom had no warning biomarkers, exhibited tumor recurrence, but all of them could be identified by the CTC numbers or PCP." (PMID 37337648, 2023). "However, biopsies are sometimes omitted in cases in which the lesion exhibits a characteristic location and tumor markers such as β-HCG and alpha-fetoprotein (AFP) show appropriate expression patterns (tests for β-HCG are negative or slightly positive and those for AFP are negative)." (PMID 24272066, 2014).
cancer (921 papers, 1981 to 2026). A tumor composed of atypical neoplastic, often pleomorphic cells that invade other tissues. "Biomarkers of cancer risk, such as alpha-fetoprotein (AFP), carbohydrate antigen 19–9 (CA 19-9), carcinoembryonic antigen (CEA), and prostate-specific antigen (PSA), are crucial in evaluating the potential health impacts of these products." (PMID 40078230, 2025). "As a particular case, elevated levels of AFP in adults indicate certain pathological conditions that include different types of malignant neoplasms, such as liver cancer, and are also associated with ovarian, gastric, and lung cancers." (PMID 41002370, 2025). "We propose tiered surveillance: annual physical exams for all patients, supplemented by biennial abdominal ultrasound and serum AFP in those with truncating mutations or family history of early‐onset cancers." (PMID 40777882, 2025). "AFP-L3, a subtype of AFP found in cancer cells, provides diagnostic specificity by measuring its proportion to total AFP (AFP-L3%)." (PMID 40227568, 2025). "The first diagnostic biomarkers to be used for cancer testing andscreening were primarily proteins such as alpha-fetoprotein (AFP)and PSA, which were discovered and developed for clinical applicationin the early stages of biomedical research." (PMID 38481702, 2024). "Higher AFP (>400 ng/mL), relapse, abdominal ascites, and a higher cancer CLIP score were associated with poorer outcomes." (PMID 38374854, 2024). "Another study showed that higher serum AFP level in the patients of cancer indicated the risk of bone metastases and thus to infer more effective cancer treatment options." (PMID 37404755, 2023). "The diagnostic value of CASC7 and AFP in differentiating patients with HCC from non-cancer (CHB + normal) was further assessed." (PMID 37735632, 2023). "Nonetheless, there are selected genetic syndromes and pediatric cancers in which AFP holds the potential for diagnostic, monitoring, and prognostic applications." (PMID 37686577, 2023). "Combining ctDNA and AFP as complementary markers presents an intriguing avenue for enhanced diagnostic and prognostic precision in cancer management." (PMID 38201440, 2023). "A preoperative serum AFP level of >1000 ng/mL was highly associated with postoperative cancer recurrence." (PMID 37519810, 2023). "ACOG recommendations include 3 biomarker assays to assess risk for these cancer subtypes: Alpha-fetoprotein (AFP), Human chorionic gonadotropin (β-HCG), and Lactic dehydrogenase (LDH)." (PMID 35865172, 2022). "Alternatively, the serum AFP level was reported to intimately associate with aggressive cancer behavior in HCC." (PMID 36077743, 2022). "In patients considered at risk for developing this type of cancer, AFP represents a powerful screening tool, combined with abdominal ultrasonography." (PMID 35497085, 2022). "Recently, a large number of tumor-associated antigens (TAAs), such as heat shock proteins, alpha-fetoprotein, and carcinoembryonic antigen, have been identified in a variety of malignant tumors." (PMID 34925334, 2021). "The trend for our findings by the two competing endpoints of all-cause and cancer-specific mortality to coincide adds to the evidence that the AFP test helps early detection of HCC." (PMID 32845895, 2020). "This study showed that higher serum IL-13 levels and higher serum AFP levels were directly associated with cancer (OR = 2.036, 95% CI = 1.384–3.076, p = 0.001) and (OR = 9.151, 95% CI = 2.94–28.425, p < 0.001), respectively." (PMID 32283835, 2020). "Alpha-fetoprotein (AFP) is a major mammalian embryo-specific and tumor-associated protein recognized as a “golden standard” among cancer biomarkers used in clinical practice." (PMID 32019136, 2020). "AFP as a tumor-associated antigen can promote the development of cancer and affect the expression of oncogene through the change of cAMP and Ca2+ concentration via binding with the cell membrane receptor." (PMID 29805966, 2018).